CCN3 (cellular communication network factor 3)
Description:
Immediate-early protein playing a role in various cellular processes including proliferation, adhesion, migration, differentiation and survival. Acts by binding to integrins or membrane receptors such as NOTCH1. Essential regulator of hematopoietic stem and progenitor cell function. Inhibits myogenic differentiation through the activation of Notch-signaling pathway. Inhibits vascular smooth muscle cells proliferation by increasing expression of cell-cycle regulators such as CDKN2B or CDKN1A independently of TGFB1 signaling. Ligand of integrins ITGAV:ITGB3 and ITGA5:ITGB1, acts directly upon endothelial cells to stimulate pro-angiogenic activities and induces angiogenesis. In endothelial cells, supports cell adhesion, induces directed cell migration (chemotaxis) and promotes cell survival. Also plays a role in cutaneous wound healing acting as integrin receptor ligand. Supports skin fibroblast adhesion through ITGA5:ITGB1 and ITGA6:ITGB1 and induces fibroblast chemotaxis through ITGAV:ITGB5. Seems to enhance bFGF-induced DNA synthesis in fibroblasts. Involved in bone regeneration as a negative regulator (By similarity). Enhances the articular chondrocytic phenotype, whereas it repressed the one representing endochondral ossification. Impairs pancreatic beta-cell function, inhibits beta-cell proliferation and insulin secretion (By similarity). Plays a role as negative regulator of endothelial pro-inflammatory activation reducing monocyte adhesion, its anti-inflammatory effects occur secondary to the inhibition of NF-kappaB signaling pathway. Contributes to the control and coordination of inflammatory processes in atherosclerosis (By similarity). Attenuates inflammatory pain through regulation of IL1B- and TNF-induced MMP9, MMP2 and CCL2 expression. Inhibits MMP9 expression through ITGB1 engagement. Brain osteoanabolic hormone (By similarity). Drives osteogenesis in osteochondral skeletal stem cells. During lactation, maintains the maternal skeleton and viability of offspring (By similarity).
Synonyms: IBP-9; IGFBP-9; NovH; IGFBP9; NOV
Tractability: Antibody: UniProt places it where antibodies can reach, with medium confidence; UniProt predicts a signal peptide or a membrane-spanning region; its Gene Ontology location is reachable by antibodies, with medium confidence.
Gene: Protein-coding gene on chromosome 8 (119,416,446 to 119,424,434, forward strand). Ensembl gene ENSG00000136999.
Subcellular location: Secreted; Cytoplasm; Cell junction, gap junction
Subcellular location (Human Protein Atlas): Vesicles; Cytosol; Predicted to be secreted
Gene Ontology:
Molecular function: integrin binding; Notch binding; protein binding; heparin binding; hormone activity
Biological process: angiogenesis; cell adhesion mediated by integrin; cell chemotaxis; chondrocyte differentiation; endothelial cell chemotaxis; endothelial cell-cell adhesion; fibroblast migration; hematopoietic stem cell homeostasis; negative regulation of cell growth; negative regulation of chondrocyte proliferation; negative regulation of monocyte chemotaxis; negative regulation of myotube differentiation; negative regulation of non-canonical NF-kappaB signal transduction; positive regulation of Notch signaling pathway; positive regulation of ossification; smooth muscle cell migration; smooth muscle cell proliferation; bone regeneration; cell adhesion; collagen fibril organization; negative regulation of inflammatory response; negative regulation of insulin secretion; negative regulation of sensory perception of pain; negative regulation of SMAD protein signal transduction; positive regulation of cell differentiation; and 5 more
Cellular component: cytoplasm; cytosol; gap junction; non-collagenous component of interstitial matrix; extracellular matrix; extracellular region
Genetic constraint (gnomAD): Loss-of-function variants: 23 observed, 33.73 expected, observed/expected ratio (o/e) 0.68, 90% interval 0.49 to 0.97. The upper end of that interval is the gene's LOEUF score, 0.97, which puts it in group 4 of 6, group 1 being the genes least tolerant of losing a copy. Missense variants: 465 observed, 472.72 expected, observed/expected ratio (o/e) 0.98, 90% interval 0.91 to 1.06. Synonymous variants: 205 observed, 176.9 expected, observed/expected ratio (o/e) 1.16, 90% interval 1.03 to 1.3.
Homologues: Orthologues: chimpanzee CCN3 (99% identical), macaque CCN3 (99% identical), rabbit CCN3 (83% identical), rat Ccn3 (81% identical), dog CCN3 (80% identical), mouse Ccn3 (80% identical), guinea pig CCN3 (79% identical), pig CCN3 (77% identical), tropical clawed frog ccn3 (57% identical). Paralogues in human: CCN2 (48% identical), CCN1 (42% identical), CCN4 (36% identical), CCN6 (34% identical), CCN5 (31% identical).
Diseases named in the same sentence as CCN3 in open-access papers:
CCN3 is named in the same sentence as 114 diseases in open-access papers, as found by Europe PMC text mining. Sharing a sentence is not in itself a finding about the gene and the disease. The quoted sentences say what the papers report.
Nephroblastoma (24 papers, 2004 to 2024). An embryonal neoplasm characterized by the presence of epithelial, mesenchymal, and blastema components. "CCN3 was discovered as a gene overexpressed in myeloblastosis associated virus (MAV)-induced nephroblastomas in chickens, and this study first reported that CCN3 is highly expressed throughout development in the brain of chickens." (PMID 32651278, 2020). "Overexpressed genes that were associated with tumor progression (proliferation factors) within this animal cohort included nephroblastoma overexpressed gene (NOV or CCN3), which has been associated with promotion of cell survival and attachment." (PMID 29259271, 2017). "Nephroblastoma Overexpressed (NOV/CCN3) was first discovered in chicken myeloblastosis-associated virus-induced nephroblastomas." (PMID 24721786, 2014). "The highly restricted oncogenic properties of MAV1(N) made it a unique tool to study nephroblastoma development at a molecular level and has led to the discovery of nov/ccn3, which encode a member of the emerging CCN family of cell growth regulators." (PMID 18558010, 2008). "In Wilms' tumors, the expression of ccn3 was a marker of differentiation whereas in Ewings' tumors, the expression of ccn3 was associated with a higher risk of developing metastasis." (PMID 16403231, 2006). "The abbreviation CCN stems from the initial three members of this family: CYR61 (CCN1), CTGF (CCN2), and NOV (nephroblastoma overexpressed/CCN3)." (PMID 38542515, 2024). "NOV (nephroblastoma overexpressed, or NOV/CCN3) is a tumor suppressor gene encoding an extracellular-matrix protein that increases cell adhesion." (PMID 33430890, 2021). "The CCN family includes CCN1/CYR61 (cystein-rich 61], CCN2/CTGF (connective tissue growth factor), CCN3/NOV (nephroblastoma overexpressed), and also CCN4/WISP-1, CCN5/WISP-2, CCN6/WISP-3 (Wnt-inducible secreted proteins)." (PMID 34940056, 2021). "Nephroblastoma Overexpressed (NOV) encodes a small secreted protein, which is a member of the CCN family of regulator proteins (CCN3)." (PMID 31014357, 2019). "The family members other than CTGF are cysteine-rich angiogenic inducer 61 (Cyr61/CCN1), nephroblastoma overexpressed genes (Nov/CCN3), and Wnt-inducible signaling pathway proteins 1–3 (WISP1-3/CCN4-6)." (PMID 30123390, 2018). "Our genomic analysis led to the identification of nephroblastoma overexpressed gene (Nov, also known as Ccn3) as a novel FoxO1 target." (PMID 23705021, 2013). "As a control we first checked that hybridization performed with these labeled RNA species permitted detection of the DNA fragments of BAC15 which contained the CCN3 gene known to be overexpressed in all MAV-induced nephroblastomas." (PMID 16403231, 2006). "Experiments performed in our laboratory have established that CCN3 is a marker of tumor differentiation in Wilms tumors and several other tumor types [unpublished observations]." (PMID 15361251, 2004). "Transgenic-adipo-PGC-1α mice displayed reduced adipocyte hypertrophy, associated with a reduction in molecules within the TGF-β signaling pathway, and of the inflammatory markers nephroblastoma-overexpressed/cellular communication network factor 3 (NOV/CCN3), Twist1, and IL-6." (PMID 35740043, 2022). "Fascial fibroblasts resemble features of fibroblasts derived from hypertrophic scars and keloids, including high expression of NOV (nephroblastoma overexpressed, or CCN3), CD26 (DPP4), and FAP (fibroblast activating protein) to produce more of the proteoglycan versican but less collagenase (MMP1)." (PMID 34445709, 2021). "Since both the MAV1- and the MAV2-induced nephroblastomas that we analyzed showed elevated levels of ccn3 expression, these conflicting observations result from either the route of injection, the time frame for injection, the different nature of the viral strains or host differences." (PMID 16403231, 2006).
Nephroblastoma (continued). "Use of junction fragments containing viral U3 and adjacent cellular sequences, permitted to establish that in one of the most developed tumor one of the proviral genome was integrated within a gene that is known as ccn3 and that we originally designated "nov" for « nephroblastoma overexpressed »." (PMID 16403231, 2006). "The CCN3 (NOV) gene had been initially characterized as an integration site for the myeloblastosis associated virus MAV which induces kidney tumors resembling nephroblastoma and Wilms tumor." (PMID 15361251, 2004). "Therefore, the elevated levels of ccn3 expression detected in all MAV-induced nephroblastomas might result from the expansion of blastemal cells that are transformed at a well defined stage of differentiation upon MAV1 infection." (PMID 16403231, 2006). "CCN3 (otherwise called NOV, nephroblastoma overexpressed) prompted improved M2 macrophage invasion, though CCN3 lack delayed xenograft survival in prostate cancer growth." (PMID 37211559, 2023). "CCN3, also known as NOV (nephroblastoma overexpressed), is a sister molecule with antagonist effects from CCN2." (PMID 37762168, 2023). "We also observed increased muscle expression of another CCN family member, CCN3, a protein also known as NOV (nephroblastoma overexpressed) that has anti-fibrotic properties." (PMID 37762168, 2023). "CCN3, previously known as NOV (nephroblastoma overexpressed), was one of the first identified members of the CCN protein family." (PMID 34940056, 2021). "For the sake of homogeneity that is required for a PhD defense, I suggested G. Chevalier to concentrate on the expression of ccn3 during the normal development of chicken kidney and in MAV-induced nephroblastomas." (PMID 16504021, 2006). "To study cortex zonation in more detail, we used nephroblastoma overexpressed/cysteine-rich protein 61/connective tissue growth factor/nephroblastoma overexpressed gene-3 (NOV, also known as CCN3) as a marker for the DZ and sulfotransferase 2A1 (SULT2A1) as a marker for the FZ." (PMID 37440461, 2023). "Initially, CCN2 was designated connective tissue growth factor (CTGF), owing to its mitogenic activity in fibroblasts, whereas the original name of CCN3 was nephroblastoma-overexpressed (NOV), since it was found to be overexpressed in a truncated form in nephroblastomas." (PMID 35682564, 2022). "One such example where the two possibilities are not yet resolved is in Wilms tumor, where CCN3 is abundantly expressed during normal nephrogenesis and in tumors." (PMID 15361251, 2004). "Interestingly, CCN3 was originally identified during MAV virus induction of nephroblastoma but is not a direct target of WT1, the Wilms tumor suppressor gene." (PMID 15361251, 2004).
prostate carcinoma (17 papers, 2006 to 2023). A carcinoma that arises from epithelial cells of the prostate gland. "Bone metastases of prostate cancer in humans express higher levels of the extracellular matrix-associated protein CCN family member 3 (CCN3) compared to the primary tumor." (PMID 34064589, 2021). "High CCN3 expression correlates with a poor prognosis in renal and prostate carcinomas, Ewing tumors, osteosarcomas and melanoma, whereas in gliomas, chronic myeloid leukemia, malignant adrenocortical tumors and neuroblastoma, high CCN3 expression is associated with a good prognosis." (PMID 29088803, 2017). "In contrast, CCN3 can suppress enzalutamide-resistant prostate cancer cell proliferation by inhibiting androgen receptor signaling in prostate cancer cells." (PMID 37373471, 2023). "CCN3 has been shown to act as a metastasis inducer by promoting the migration of cancer cells in glioblastoma, Ewing’s sarcoma, melanoma, chondrosarcoma, prostate cancer, clear cell renal cell carcinoma, and hepatocellular carcinoma." (PMID 36737605, 2023). "Consistently, a knockdown of CCN3 was found to decrease bone metastasis of prostate cancer cells since CCN3 upregulates the expression of the pro-migratory intercellular adhesion molecule 1 (ICAM-1) and promotes migration via AKT, NFKB, and other pathways." (PMID 34064589, 2021). "NOV/CCN3 decreased expression was already described in various tumor types and cancer cell lines including prostate cancer LNCaP cells." (PMID 33430890, 2021). "In prostate cancer, CCN3 is a potential therapeutic target for prevention of bone metastasis via inhibition of the FAK/Akt/p38/NF-κB signaling pathway." (PMID 29061995, 2017). "Previous studies have shown that CCN3 expression is upregulated in prostate cancer (PCa) cells and in PCa patients." (PMID 29088803, 2017). "CCN3 has been demonstrated to have prometastatic potential in prostate cancer in our previous study." (PMID 24551846, 2014). "Experiments with intratibia injection of prostate cancer cells also proved that CCN3 enhanced osteoclast activity and bone metastasis in vivo." (PMID 24551846, 2014). "It is intriguing to note that the highest level of CCN3 expression was observed in the PC3 prostate cancer cell line, which forms aggressive osteolytic bone metastases when injected into mice." (PMID 22427255, 2012). "Only one study has examined CCN3 levels in prostate cancer cell lines and tissues, which revealed that CCN3 expression was higher in prostate cancer-derived cell lines compared to immortalized prostate epithelial cells." (PMID 22427255, 2012). "Relatively little is known concerning the role of CCN3 in prostate cancer progression and metastasis." (PMID 22427255, 2012). "We suggest that increased levels of PVT1 in advanced prostate cancer tumors could modulate an enhanced epigenetic inhibitory effect of AR on NOV/CCN3 expression, through the AR-EZH2-PVT1 axis." (PMID 33430890, 2021). "Prostate cancer cells with a high CCN3 expression were shown to preferably metastasize to the bone." (PMID 34064589, 2021). "CCN3 in conditioned medium from prostate cancer cells favours osteoclastogenesis via both RANKL-dependent and RANKL-independent pathways in vitro and forced overexpression of CCN3 in PCa and LnCAP C4-2 cells enhances osteolytic potential and TRAP-staining in metastatic lesions." (PMID 34228239, 2021). "CCN3 may inhibit the activity of NOTCH1 by binding to the extracellular domain of NOTCH1 in CML, and the CCN3 protein secreted by prostate cancer (PCa) could recruit macrophages and promote their differentiation into the M2 phenotype." (PMID 34393649, 2021). "In prostate cancer, CCN3 induces ICAM-1 expression and thus promotes bone metastasis." (PMID 28903329, 2017). "Here, we found that CCN3 promoted Twist expression in prostate cancer cells." (PMID 29088803, 2017). "Our findings provide insight into the involvement of CCN3 in the EMT regulation of prostate cancer." (PMID 29088803, 2017).
prostate carcinoma (continued). "This work provides novel insights into CCN3 that may encourage its development as a therapeutic target, as a means of preventing bone metastasis in prostate cancer." (PMID 29088803, 2017). "An immunohistochemistry study on normal prostate tissues, primary tumors, and bone metastasis samples obtained from patients revealed that CCN3 expression levels were higher in patients with bone metastasis and positively correlated with malignancy in human prostate cancer cells." (PMID 24551846, 2014). "CCN4 has been shown to play similar roles to CCN3 in prostate cancer." (PMID 24551846, 2014). "Moreover, very little is known regarding the role of CCN3 in prostate cancer progression and subsequent metastasis to bone." (PMID 22427255, 2012). "Additionally, prostate cancer-secreted CCN3 was shown to mediate RANK upregulation in osteoclast precursors via the FAK/AKT/mitogen-activated protein kinase 11 (p38)/NF-κB axis and, thus, promotes the RANKL-dependent osteoclastogenesis and tumor-induced osteolysis." (PMID 34064589, 2021). "In addition, CCN3 (also known as NOV, nephroblastoma overexpressed) led to enhanced M2 macrophage infiltration, whereas CCN3 deficiency prolonged xenograft survival in prostate cancer." (PMID 31300030, 2019). "Moreover, our latest study revealed the critical role of CCN3 in prostate cancer bone metastases." (PMID 24551846, 2014). "However, this will require further functional validation to determine whether CCN3 plays a functional role in prostate cancer growth and metastasis to bone." (PMID 22427255, 2012). "CCN2, as observed in breast cancer, CCN3 and CCN4 levels are up regulated in prostate cancer and bone-metastatic cells or corresponding bone metastasis." (PMID 34228239, 2021). "Furthermore, CCN3 also promoted ICAM-1 expression and cell motility of human prostate cancer cells." (PMID 23803661, 2013).